DCD (dermcidin)
Diseases named in the same sentence as DCD in open-access papers (continued):
Sharing a sentence is not in itself a finding about the gene and the disease.
hidradenitis suppurativa (1 paper, 2022). A chronic suppurative and cicatricial disease of the apocrine glands occurring chiefly in the axillae in women and in the groin and anal regions in men. "DCD actively participates in cutaneous innate immune defence, low levels of this AMP have been associated with conditions like atopic dermatitis or hidradenitis suppurativa." (PMID 36544771, 2022).
infertile (1 paper, 2018). "Their results demonstrated 10 over-expressed proteins in the infertile group, including: Ubiquitin-conjugating enzyme E2C binding protein (UBE2C), Cystatin-A (CSTA), Dermcidin (DCD), Ceruloplasmin (CP), Ras GTPase-activating-like protein IQGAP1 (IQGAP1)." (PMID 29881623, 2018).
lymph node metastasis (1 paper, 2021). "Positive dermcidin patients showed a significantly high frequency of lymph node metastasis." (PMID 34198581, 2021). "In addition, dermcidin-positive patients showed an unfavorable clinical behavior and a high frequency of lymph node metastasis." (PMID 34198581, 2021). "In addition, the dermcidin-positive group also showed a high frequency of dermal invasion and lymph node metastasis." (PMID 34198581, 2021).
osteoarthritis (1 paper, 2021). A noninflammatory degenerative joint disease occurring chiefly in older persons, characterized by degeneration of the articular cartilage, hypertrophy of bone at the margins and changes in the synovial membrane. "Of note, previous reports have identified various CAMPs in synovial fluid, including the cathelicidin LL-37, β defensins, and dermcidin, although the expression levels of the peptides vary depending on the disease type (rheumatoid/osteoarthritis) and infection status." (PMID 33692196, 2021).
pneumonia (1 paper, 2023). An acute, acute and chronic, or chronic inflammation focally or diffusely affecting the lung parenchyma, caused by an infection in one or both of the lungs (by bacteria, viruses, fungi, or mycoplasma.). "Therefore, DCD‐containing BM‐MSC‐derived migrasome is a eutherapeutic therapy against post‐stroke pneumonia, which is superior to DCD protein as far as we are concerned." (PMID 37246283, 2023).
psoriasis (1 paper, 2024). An autoimmune condition characterized by red, well-delineated plaques with silvery scales that are usually on the extensor surfaces and scalp. "Abnormal levels of DCD are implicated in the pathogenesis of psoriasis and AD." (PMID 38606161, 2024).
thyroid cancer (1 paper, 2023). "Among them, KRT1B protein, dermcidin and keratin, type II cytoskeletal 5 are not well addressed in thyroid cancer." (PMID 37101287, 2023).
viral infection (1 paper, 2023). "Recently, we further confirmed that viral infection led to a shift toward virus-specific sphingolipids, which is consistent with the downregulation of genes involved in the host de novo sphingolipid biosynthesis, such as serine palmitoyltransferase (SPT), ceramide synthetase (CERS), and DCD genes." (PMID 37761856, 2023).
tumor (29 papers, 2001 to 2025). "Recent studies have shown that many new proteins, such as dermcidin, are involved in tumor formation and metastasis and are directly associated with tumor development." (PMID 35188865, 2022). "As DCD appears to encode both putative tumour survival and cachectic factors, it represents an important potential therapeutic target in cancer patients." (PMID 18594538, 2008). "Despite this protective function, dermcidin has been reported at high expression levels with a suggested survival-promoting activity in select cancers, but its role in carcinogenesis and tumor maintenance is still unclear." (PMID 34885944, 2021). "Although induction of oxidative stress or hypoxia, two conditions found in the tumour microenvironment, seemed to result in an upregulation of DCD expression in several cancer cell lines, the CT values remained in the low/absent range." (PMID 18594538, 2008). "As such, the role of DCD expression between different tumour types and within the same tumour type is difficult to ascertain." (PMID 18594538, 2008). "The results presented here demonstrate that DCD mRNA expression varies both between tumour types and within primary tumours of the same type." (PMID 18594538, 2008). "The aim of this study was to evaluate dermcidin expression in cell lines following simulation of tumour microenvironmental conditions and in a range of primary tumours." (PMID 18594538, 2008). "Moreover, the three groups showed a reduction in tumor-derived molecule proteolysis-inducing factor/dermcidin (p = 0.021)." (PMID 40430444, 2025). "Moreover, additional effort is required to understand the role of dermcidin in tumor cell survival and resistance." (PMID 34885944, 2021). "Thus, this study aimed to evaluate the expression of DCD mRNA (as a surrogate of Y-P30/PIF-CP expression) using quantitative real-time PCR in a range of primary tumours." (PMID 18594538, 2008). "Tumour tissues were collected from patients with oesophageal (28 samples), gastric, pancreatic (five), bile duct (one) and prostatic carcinomas as well as 30 benign tissue samples, for assessment of dermcidin mRNA levels using real-time PCR." (PMID 18594538, 2008). "These factors make the evaluation of the role of DCD in human tumour biology elusive." (PMID 18594538, 2008). "However, the detailed molecular mechanism determining whether dermcidin promotes such tumor cell migration remains unclear." (PMID 34198581, 2021). "One of the reasons behind this might be that dermcidin contributes to the development of the tumor." (PMID 34198581, 2021). "Taken together, these evidences confirm that these HEMTIRGs (CRISP3, PAX7, FGG, and DCD) are closely related to hypoxia, EMT, and tumor immunity, which in turn contribute to the regulation of BC pathogenesis and prognosis." (PMID 41200166, 2025). "Immunohistochemistry of primary tumor tissue was performed for eight proteins: COL6A6, DCD, GBP4, KLHL41, KRT9, PIP, SCGB1D2, SCGB2A2." (PMID 34757537, 2022). "The mean survival times were different between positive and negative dermcidin expression in the tumor." (PMID 34198581, 2021). "Expression of dermcidin in human primary tumours appears highly variable and is not induced substantially by hypoxia/oxidative stress in cell line model systems." (PMID 18594538, 2008). "In their study, samples from three groups (PA, residual PA, and CXPA) were analyzed to identify protein signatures and their results suggested that seven proteins (APOA1, AP1M1, SYCP1, DCD, HBB, HP, and SLC4A1) could be potential signatures for tumor progression or suppression." (PMID 39155517, 2025). "The substantial variability of DCD expression in primary tumours and cell lines and lack of reliable methods of DCD induction in vitro may require development of new model systems (perhaps based on the MIA-Pa-Ca-2 cell line) and novel detection methods for the DCD protein itself." (PMID 18594538, 2008).
cancer (22 papers, 2001 to 2024). A tumor composed of atypical neoplastic, often pleomorphic cells that invade other tissues. "Dermcidin is associated with cancer survival, including in PCa." (PMID 39336161, 2024). "Collectively, these findings clearly demonstrate the involvement of DCD in the survival and drug resistance of various cancers." (PMID 38773230, 2024). "In 2012, the protein dermcidin (DCD) was shown to induce drug resistance to anti-cancer drugs and play a role in cancer metastasis." (PMID 38773230, 2024). "Cytotoxicity of seriniquinones was demonstrated through binding to dermcidin, a small protein involved in cancer cell proliferation and induction of cell death via autophagocytosis." (PMID 37446864, 2023). "Although there are solid data that link dermcidin and cancer, the proper role of the protein at molecular levels and its contribution to tumorigenesis is still unclear." (PMID 35621952, 2022). "Dermcidin has also been reported as a biomarker in various diseases in addition to malignant tumors." (PMID 34198581, 2021). "In contrast to its beneficial effect on the human body, however, dermcidin can also play an important role in the development of malignant tumors and other diseases." (PMID 34198581, 2021). "Further studies have shown that knockdown of DCD in breast and lung cancer cell lines repressed cell proliferation and tumorigenesis, therefore reinforcing its relevance for cancer progression." (PMID 34885944, 2021). "It has been reported that dermcidin is a cancer cachectic and proteolysis inducing factor (PIF); it was also found to overexpress in malignant proliferative cells." (PMID 31300527, 2019). "Dermcidin acts as a survival factor in a variety of cancer cell lines under hypoxia or oxidative stress." (PMID 18594538, 2008). "Assessment of 58 gastric and oesophageal biopsy samples showed that DCD mRNA expression occurred in a small percentage of gastro-oesophageal malignancy and that expression levels were minimal." (PMID 18594538, 2008). "Dermcidin and PIF-CP have been implicated in cancer cell survival in a range of different types of cancer." (PMID 18594538, 2008). "It targets the unique small protein, dermcidin, which affects the drug resistance of cancer cells." (PMID 38773230, 2024). "Besides the well-established role for the dermcidin in skin defense, this protein has been described as a cancer survival factor with overexpressed in select tumors." (PMID 34885944, 2021). "As such, it could be speculated that there may be low or absent pan-cellular DCD expression with a small subset of immortalised cancer cells expressing some DCD." (PMID 18594538, 2008). "Finally, to determine if DCD expression is upregulated in response to stressors found in the cancer microenvironment, we have analysed changes in the expression of DCD mRNA in prostate and pancreatic cell lines in vitro in response to hypoxia or oxidative stress." (PMID 18594538, 2008). "Dermcidin (DCD), ezrin (EZR), and prosaposin (PSAP) are also hyper-secreted in both R273H- and R175H-driven secretome samples and they promote cancer progression." (PMID 32526853, 2020). "Previously it has been delineated from our laboratory that dermcidin could induce anomalous platelet aggregation in AIHD and also impaired nitric oxide and insulin activity and furthermore dermcidin was also found in a few types of cancer patients." (PMID 31300527, 2019).
infection (4 papers, 2009 to 2024). The state of being infected such as from the introduction of a foreign agent such as serum, vaccine, antigenic substance or organism. "DCD actively participates in the constitutive innate immune defence of human skin against infection." (PMID 39020369, 2024). "Eccrine sweat glands are known for their function in thermoregulation but also for being part of innate immune defense of human skin against infection, due to production of the antimicrobial peptide dermcidin (DCD)." (PMID 34177874, 2021).
metabolic disorders (3 papers, 2019 to 2024). "Other milk hormones, such as chemerin and dermcidin, were discovered relatively recently, and little is known about their changes in relation to maternal metabolic disorders." (PMID 39795898, 2024).
DCD also shares sentences with these, for which no sentence is quoted: diabetes mellitus (2 papers); invasive breast carcinoma (2); Autoimmunity (1); bacterial infections (1); cardiac diseases (1); cardiovascular disease (1); cerebral (1); colorectal carcinoma (1); endometrial carcinoma (1); essential hypertension (1); facioscapulohumeral muscular dystrophy (1); heart failure (1); ichthyosis (1); melanocytic nevus (1); muscle atrophy (1); muscular dystrophy (1); obstructive sleep apnea (1); pancreatic adenocarcinoma (1); sarcopenia (1); Stroke (1); superficial spreading melanoma (1).